STAT3 (signal transducer and activator of transcription 3)
Diseases named in the same sentence as STAT3 in open-access papers (continued):
Sharing a sentence is not in itself a finding about the gene and the disease.
cancer (continued). "In the present study, GO-Y031 targeted both β-catenin and STAT3, which are transcriptional regulators that control various downstream molecules, such as c-Myc, cyclin D1, vascular endothelial growth factor, and survivine, and contribute to cancer cell growth and survival." (PMID 25331984, 2015). "Importantly, these anti-cancer effects of Lycorine are dependent on STAT3 expression." (PMID 25915156, 2015). "Although STAT3 may play a vital role in early embryogenesis, its presence in the vast majority of adult cells is largely expendable, thus make it an attractive target for certain cancer therapies." (PMID 24297508, 2014). "Therefore, we employed western blot to test whether the suppression of STAT3 signaling pathway was involved in the TMOC-mediated anti-cancer effects." (PMID 25180593, 2014). "Thus, targeting acetylation of STAT3 using small molecule approach could be a potential means for chemoprevention and cancer therapy." (PMID 24655440, 2014). "Moreover, small molecules that induced synthetic lethality in KRAS mutant cancer cells were found to be a novel class of STAT3 inhibitors, demonstrating that genetic interaction between Ras and STAT3 pathways can be explored for genotype-specific anticancer therapeutics." (PMID 24662938, 2014). "Consequently, STAT3 is an attractive target for pharmacologic intervention in cancer patients." (PMID 24657910, 2014). "Thus, STAT3 can be a friend or foe, depending on the pathogenesis of specific types of cancer." (PMID 24995504, 2014). "In addition, STAT3 activation was reported to regulate ARG1 in MDSCs isolated from cancer patients." (PMID 25238263, 2014). "Exploiting genetic interactions of STAT3 with other cancer-related pathways may provide molecular insight into mechanisms of cancer resistance to pathway-targeted therapies and strategies for development of more effective anticancer agents and treatment regimens." (PMID 24662938, 2014). "Thus, STAT3 inhibitors may be used as chemopreventive agents for the prevention of cancers of colon, lung, prostate, pancreas, ovary and hematopoietic origin." (PMID 24743778, 2014). "Due to the critical role of STAT3 in maintaining stem cell self-renewal in carcinogenesis, it is rational to speculate that STAT3 blockade may be able to significantly or permanently eliminate CSCs to achieve cancer prevention purpose." (PMID 24743778, 2014). "It is possible that potential STAT3-deficient cancer cells in this model may not have survived the repeated DSS treatments in the CAC model." (PMID 24995503, 2014). "However, the regulatory mechanisms that negatively modulate STAT3 are ineffective in cancers." (PMID 25417721, 2014). "However, neither obesity nor activation of IL-6/STAT3 cause cancer on their own, but increase the possibility of progression to cancer of hepatocytes that have earlier acquired an oncogenic mutation." (PMID 25533006, 2014). "Therefore, inhibition of the Stat3/Cx axis might be beneficial at late stages of cancer progression." (PMID 24670366, 2014). "Moreover, ROS induces the transcriptional activity of STAT3 in autophagy activated cancer cells." (PMID 24796733, 2014). "Thus, in the context of cancer biology, STAT3 can be a friend or foe." (PMID 24995504, 2014). "Therefore, interaction between FTO and STAT3 may suggest potential implication of FTO in cancer development, as it has already been suggested." (PMID 24410832, 2014). "Consequently, STAT3 has gained attention as a promising target for cancer immunotherapy." (PMID 24806510, 2014). "However, since curcumin has diverse biological effects and targets multiple signal transduction pathways including NF-κB and STAT3, poor bioavailability, and relatively low anti-cancer potency, several more selective and potent analogs of curcumin have been developed." (PMID 23940701, 2013). "Therefore, STAT3 inhibitors may be useful for reversal of cancer-induced immunosuppression through acting on both cancer cells and various immune cells." (PMID 23755373, 2013).
cancer (continued). "Therefore, IL-6R overexpression, coupled with enhanced IL-6/STAT3 signaling may facilitate the malignant transformation of EBV-infected premalignant NPE cells into cancer cells, and enhance malignant properties of NPC cells." (PMID 23658720, 2013). "Interestingly, several protein tyrosine phosphatases that can deactivate STAT3 signaling through direct dephosphorylation of p-STAT3 (Tyr 705) might be useful targets for induction of cancer cell death." (PMID 23938089, 2013). "Besides direct inhibition of STAT3, inhibitors of the molecules regulating STAT3 activation may also be effective for the reversal of cancer-induced immunosuppression." (PMID 23755373, 2013). "In addition, uPA was identified as a key molecule regulated by STAT3 in wound healing and cancer." (PMID 23326564, 2013). "Therefore, our findings suggest that scoparone could represent a novel chemotherapeutic agent against cancers that harbor constitutively active STAT3." (PMID 24260381, 2013). "In addition, constitutive activation of STAT3 has been reported in many cancers." (PMID 24288468, 2013). "Collectively, these findings suggest that targeting STAT3 may be a promising anti-cancer strategy." (PMID 23938089, 2013). "This hypothesis is in agreement with a recent report demonstrating that STAT3 signaling promotes somatic cell reprogramming by epigenetic regulation and may provide a link between the inflammatory response, epigenetic remodeling and cancer development." (PMID 24344100, 2013). "Therefore, blockage of STAT3 may have a therapeutic potential in preventing and treating these cancers." (PMID 23533997, 2013). "Blockade of the JAK/STAT3 signal may inhibit the growth of human cancers." (PMID 24116074, 2013). "STAT3 may also play a critical role in chemoresistance in a number of cancer types, including OS." (PMID 23244668, 2012). "In addition to its diverse biological functions including roles in cell proliferation, differentiation, apoptosis, inflammation, and oncogenesis, accumulating evidence suggests that STAT3 also plays an important role in cancer angiogenesis under both physiological and pathological situations." (PMID 22530037, 2012). "Thus, STAT3 is considered as a valuable therapeutic target molecule for cancer treatment." (PMID 22260501, 2012). "All these results indicated that STAT3 might mediate tamoxifen resistance of cancer stem cells." (PMID 23554768, 2012). "Furthermore, we evaluated whether EP can affect on constitutive STAT3 activation in other cancer cell lines." (PMID 22260501, 2012). "IL-6 has been shown to induce STAT3 phosphorylation and may play a role in cancer development." (PMID 23056374, 2012). "Similarly, STAT3 targeted efficacies were reported by potent natural compounds such as ursolic acid, guggulsterone, genipin and compound K in various cancer cells." (PMID 22493659, 2012). "Our present study shows that IL-22 affects several important functions of OSCC cells via the STAT3-dependent and/or -independent pathways, suggesting that IL-22 may play a role in carcinoma cell differentiation and the upregulation of SERPINB3/B4, well-known biomarkers for SCC." (PMID 22922995, 2012). "However, in cancer pathogenesis there is evidence that STAT3 and STAT5 have similar functions." (PMID 21680956, 2011). "Our biochemical and genetic studies clearly demonstrated that Jak2/Stat3, in combination with other IL-6 downstream pathways, contributed frequently and substantially to IL-6 autocrine production in a broad spectrum of cancer cell lines as well as in clinical cancer samples." (PMID 21122157, 2010). "The rapid dephosphorylation of Stat3 that occurs following UVB would serve to increase susceptibility to UVB-mediated apoptosis and thereby limit survival of keratinocytes with DNA damage that could lead to mutations and cancer development." (PMID 20421975, 2010).
cancer (continued). "However, naturally occurring mutations in STAT3 protein resulting in its constitutive activation have not been identified, suggesting that aberrant growth factor signalling, frequent in cancer, may regulate the constitutive activation of STAT3." (PMID 19088723, 2009). "As such, STAT3 may represent a novel target for therapeutic intervention in several cancers." (PMID 19284568, 2009). "Whether this is due to the fact that the activation of STAT3 is very transient, as it has been reported for example for the human epithelial carcinoma cell line A431, or if the activation of this transcription factor through ErbB receptors plays no role in hepatocytes, has still to be clarified." (PMID 19662154, 2009). "Thus, inhibitors of STAT3 activation have potential for both prevention and therapy of cancer." (PMID 18827820, 2008). "Our study reveals that NET-DNA promotes STAT3 phosphorylation via CCDC25, thereby facilitating cancer cell EMT and chemoresistance, consistent with the fact that cancer cell EMT reduces chemotherapeutic sensitivity." (PMID 41480760, 2026). "Network analysis highlighted STAT3, EGFR, SRC, IL-6, and AKT1 as key hub targets, with enrichment in cancer-related, EGFR resistance, and PI3K-Akt pathways." (PMID 42123459, 2026). "PLK1 has emerged as a key regulator of multiple transcription factors, including STAT3, c-Myc, FOXM1, and β-catenin, positioning it as a promising combinatorial therapeutic target for disrupting oncogenic signaling networks in cancer." (PMID 41539998, 2026). "Elevated NETs hinder treatment efficacy by binding cancer cell CCDC25, leading to STAT3 activation and inducing EMT." (PMID 41480760, 2026). "Synergism of YAP/TAZ with Wnt/β-catenin and Notch pathways promotes the maintenance of cancer stem cells (CSCs) and EMT, and collaboration with STAT3 potentiates proinflammatory cytokines, like IL-6." (PMID 41476776, 2026). "In this study, the link between increased levels of PRL observed during pregnancy, overactivation of the PRL/STAT3/JAG1 pathway in CRC, and increased EMT and cancer cell stemness was established by in vitro and in silico experimentation." (PMID 41501898, 2026). "In vitro data was then used to link pregnancy levels of PRL to increased JAK2/STAT3 and JAG1/NOTCH1 signaling resulting in increased epithelial-to-mesenchymal transition (EMT) and cancer cell stem-like protein expression." (PMID 41501898, 2026). "STAT3 also influences the expression of EMT-related proteins and signaling pathways that promote cell survival in suspension, contributing to aggressive cancer phenotypes through anoikis resistance." (PMID 41596231, 2026). "For the first time, we demonstrate that pregnancy-level PRL directly enhances JAK2/STAT3 and JAG1/NOTCH1 signaling in CRC cells, promoting epithelial-mesenchymal transition (EMT) and cancer stem-like protein expression." (PMID 41501898, 2026). "Pan-cancer analyses revealed that RIPK2 exacerbates cytotoxic T-lymphocyte dysfunction and promotes resistance to immunotherapies through the JAK/STAT3 signaling pathway and γ-interferon response." (PMID 41563982, 2026). "EGCG prevents the acquisition of cancer stem cell phenotypes in ovarian cancer tumorspheres by inhibiting Src and JAK/STAT3 signaling pathways." (PMID 41608512, 2026). "Once activated, STAT3 can induce the expression of NRF2, enhancing the cancer cells’ antioxidant and detoxifying capacity." (PMID 41333220, 2025). "The results suggest that SERPINE1-mediated cancer-derived exosomal let-7 g-5p downregulates SOCS7 protein levels, reducing its interaction with STAT3, which leads to STAT3 hyperphosphorylation and promotes M2 polarization." (PMID 39748408, 2025). "While reducing anti-cancer immunity, STAT3 and, to a lesser degree, STAT5 promotes cancer cell growth, survival, and invasion." (PMID 40420174, 2025). "For instance, galactomannan from plant extracts stimulates STAT3, MAPK, and NF‐κB cascades, resulting in the inhibition of cancer cell activity." (PMID 39898127, 2025).
cancer (continued). "Recent studies have provided compelling evidence regarding IVM’s mechanisms of action in cancer cells, demonstrating its capacity to modulate multiple oncogenic signaling pathways, including Wnt/β-catenin, PI3K/Akt/mTOR, and STAT3." (PMID 41155573, 2025). "CD24 and CD44 surface markers regulate phosphorylation and acetylation of signal transducer and activator of transcription-3 (STAT3), maintaining stemness and EMT of cancer cells." (PMID 39860065, 2025). "Oncrasin-72 exerts its activity by inhibiting C-terminal domain phosphorylation of RNA polymerase II in sensitive human cancer cells, thereby activating JNK, suppressing JAK2/STAT3 phosphorylation, and reducing cyclin D1 expression." (PMID 40867324, 2025). "Among these transcription factors, STAT3 participates in the JAK/STAT pathway, in which it is activated and regulates genes related to promoting essential processes for cancer, such as the regulation of cell proliferation and survival." (PMID 41090323, 2025). "Mechanistic studies revealed FS targets key molecules (STAT3, EGFR, ESR1, PTGS2, NF-κB1, and JUN), modulating PI3K-Akt, MAPK and cancer-related pathways." (PMID 40649400, 2025). "Additionally, STAT3’s involvement in promoting tumorigenesis and resistance to therapy also supports the hypothesis that targeting STAT3 is a promising therapeutic approach for cancer therapy." (PMID 40075607, 2025). "VEGFR-2 promotes cancer stem cell proliferation and self-renewal through the VEGF/Neuropilin-1 and VEGFR-2/STAT3 pathways." (PMID 40136433, 2025). "Recent studies have shown that activation of signal transducer and activator of transcription 3 (STAT3) and HIF-1α in innate immune B cells stimulated by lipopolysaccharide (LPS) can exacerbate cancer metastasis." (PMID 40430040, 2025). "VEGFR-1 promotes cancer cell proliferation, migration, and invasiveness, while VEGFR-2/STAT-3 signaling facilitates stem cell renewal." (PMID 40136433, 2025). "Overall, these findings are important because the interaction between STAT3 and HIF plays a key role in cancer and inflammation, with both pathways frequently upregulated." (PMID 40806360, 2025). "We found that the expression of only TRXR1, mTOR pS2448, STAT3 and STAT3 pS727 proteins in ovarian SKOV-3/CDDP cancer cells treated with CUR followed by CDDP were downregulated, which led to induction of cell death in these cells." (PMID 39859517, 2025). "Among the STAT protein family, STAT1, STAT3, and STAT5 are considered to have important roles in cancer cells." (PMID 40364836, 2025). "(ii) Various investigations have demonstrated that B7-H3 regulates cancer progression through multiple signaling pathways including, JAK2/STAT3, NF-Κb, PI3K/AKT, and ERK." (PMID 41440959, 2025). "The role of the CRP is of significance, given that it has been identified as a potential mediator of carcinogenesis and cancer progression via the activation of the FcgRs/MAPK/ERK, FcgRs/NF-kB/NLRP3, and FcgRs/IL-6/AKT/STAT3 pathways." (PMID 40076898, 2025). "In pathological conditions such as cancer, colitis, and autoimmune diseases, activation of the IL11–JAK/STAT3 axis promotes inflammation, tissue remodeling, and even immunosuppression within the tumor microenvironment." (PMID 41487426, 2025). "Out of them, STAT3 (signal transducer and activator of transcription 3) inhibitors, flavonoid compounds extracted from the seeds of Silybum marianum, could play a role in reducing the toxicity of ongoing anti-cancer treatments and increasing the therapeutic potential of innovative antitumor drugs." (PMID 41441207, 2025). "Curcumin modulates the expression of several cancer targets, including cyclooxygenase-2 (COX-2), nuclear factor kappa B (NF-κB), STAT-3, tumor necrosis factor-α (TNF-α), and cyclin D1 and is found to decelerate cell growth through cell death and cycle arrest." (PMID 40563255, 2025).
cancer (continued). "In recent years, studies have shown that STAT3 interact with lncRNA, such as FGD5-AS1, LINC00908, and FOXD2-AS1 to regulate the occurrence and development of cancer." (PMID 41208976, 2025). "Several mechanisms have been implicated in TKI resistance in HCC, including activation of EGFR, PI3K/AKT, MAPK, and JAK/STAT3 pathways, EMT, hypoxia, cancer cell stemness and metabolic reprogramming." (PMID 40715090, 2025). "By modulating key signaling pathways like STAT3, targeting novel proteins such as RAC2, and interfering with cancer cell metabolism, silibinin demonstrates its potential as a multifaceted therapeutic agent." (PMID 40490812, 2025). "The observed inhibition of key oncogenic pathways, such as PI3K/AKT, STAT3, and MAPK, aligns with CSE’s demonstrated effects on cancer cell proliferation in our experimental models." (PMID 39861616, 2025). "Inflammatory processes induce elevated levels of pro-inflammatory molecules, such as cytokines (IL-6, IL-2), transcription factors (NF-κB, STAT3), and protein kinase B (AKT), which contribute to cancer initiation and progression." (PMID 39949739, 2025). "The findings reveal key mechanisms that support cancer cell survival and adaptability, including FAO- and AKT-dependent migration, STAT3 activation, MMP-9-mediated invasiveness, and mitochondrial remodeling." (PMID 40485730, 2025). "We have also highlighted different signaling pathways, including molecules such as STAT3, SKA1, LPAR1 and Wnt β-catenin and their involvement in cancer development through the ZFAS1/miRNAs/mRNAs axis." (PMID 40109869, 2025). "Researchers are developing JAK2 inhibitors (such as ruxolitinib), STAT3 inhibitors, and MYC inhibitors as new treatment options for cancer patients." (PMID 40944417, 2025). "In prostate tumors, the activation of STAT3 signaling enhances glycolysis and proliferation in cancer cells, inhibits apoptosis, induces EMT mechanisms to facilitate cancer metastasis, and additionally activates drug resistance pathways." (PMID 40052129, 2025). "It tampers with key signals, including IL-6/STAT3, NF-κB, and ERK1/2, to limit immunosuppressive macrophages and disable cancer-cell survival pathways." (PMID 40490812, 2025). "By modulating critical oncogenic pathways, inducing G1 phase arrest, and inhibiting STAT3 signaling pathway, APE effectively suppresses cancer cell proliferation and colony formation." (PMID 40278288, 2025). "CAFs in esophageal cancer secrete IL-6, IL-8, CCL5, CXCL1, and TGF-β, leading to the activation of signaling pathways such as Akt, STAT3, ERK1/2, and NF-κB, which affect cancer cell survival, proliferation, and migration." (PMID 40136652, 2025). "AhR stimulates IL-6–dependent STAT3 signaling, which maintains IDO1 expression and thereby immunosuppression in several human cancers." (PMID 40789452, 2025). "Since STAT3, MYC, and EBNA1 are each essential for survival and proliferation of EBV-transformed and cancer cells, we tested the effects of the three inhibitors on cell viability and apoptosis in EBV+ HH514–16 BL cells." (PMID 40354417, 2025). "Both STAT3 and HK2 are critical components of the Warburg effect, contributing to altered glucose metabolism in cancer cells." (PMID 39859445, 2025). "Currently, U.S. Food and Drug Administration (FDA)-approved STAT3 inhibitors primarily target the dimerization of STAT3 by binding to the STAT3 SH2 domain and are restricted to cancer therapy." (PMID 40969747, 2025). "Focusing on 14-3-3ζ which was reported to be highly expressed in various cancers, we found that BA also inhibited the binding of 14-3-3ζ to TSC2, Rictor, Raptor, mTOR, FOXO1, FOXO3a, and STAT3." (PMID 40316727, 2025). "Typically, activation of STAT3 is triggered by JAK, located downstream of the IL-6 receptor; however, recent studies revealed that STAT3 can also be activated by direct interaction with FAK, in lymphatic endothelial cells and cancer cells." (PMID 41050684, 2025).